RNF141 (ring finger protein 141)
Description:
May be involved in spermatogenesis.
Synonyms: ZNF230; ZFP26; RFP141
Tractability: PROTAC: ubiquitination databases record sites on it; its protein half-life has been measured.
Gene: Protein-coding gene on chromosome 11 (10,511,673 to 10,541,334, reverse strand). Ensembl gene ENSG00000110315.
Subcellular location: Membrane
Subcellular location (Human Protein Atlas): Microtubules; Nucleoplasm
Gene Ontology:
Molecular function: protein binding; ubiquitin-protein transferase activity
Biological process: protein autoubiquitination
Cellular component: membrane
Genetic constraint (gnomAD): Loss-of-function variants: 11 observed, 15.91 expected, observed/expected ratio (o/e) 0.69, 90% interval 0.43 to 1.14. The upper end of that interval is the gene's LOEUF score, 1.14, which puts it in group 5 of 6, group 1 being the genes least tolerant of losing a copy. Missense variants: 170 observed, 206.7 expected, observed/expected ratio (o/e) 0.82, 90% interval 0.73 to 0.93. Synonymous variants: 62 observed, 71.56 expected, observed/expected ratio (o/e) 0.87, 90% interval 0.7 to 1.07.
Homologues: Orthologues: macaque RNF141 (100% identical), mouse Rnf141 (99% identical), chimpanzee RNF141 (98% identical), pig RNF141 (98% identical), rabbit RNF141 (97% identical), guinea pig RNF141 (96% identical), dog RNF141 (82% identical), tropical clawed frog rnf141 (81% identical), zebrafish rnf141 (76% identical), Caenorhabditis elegans F54B11.5 (25% identical).
Diseases named in the same sentence as RNF141 in open-access papers:
RNF141 is named in the same sentence as 7 diseases in open-access papers, as found by Europe PMC text mining. Sharing a sentence is not in itself a finding about the gene and the disease. The quoted sentences say what the papers report.
Barrett’s esophagus (1 paper, 2021). Esophageal lesion lined with columnar metaplastic epithelium which is flat or villiform. "Another study shows that there is an increased expression of RNF141 in Barrett’s esophagus or esophageal adenocarcinoma than that in normal esophagus." (PMID 34345014, 2021).
chronic obstructive pulmonary disease (1 paper, 2022). A chronic and progressive lung disorder characterized by the loss of elasticity of the bronchial tree and the air sacs, destruction of the air sacs wall, thickening of the bronchial wall, and mucous accumulation in the bronchial tree. "The two other DMRs were common with SBP: overlapping RNF141 and C6orf138 (PTCHD4), a gene found to be sensitive to transmitted adaptation to stress and associated with chronic obstructive pulmonary disease (COPD)." (PMID 36266660, 2022).
colorectal cancer (1 paper, 2021). A primary or metastatic malignant neoplasm that affects the colon or rectum. "RNF141 is a member of RNFs family; however, its clinical significance, roles, and mechanism in colorectal cancer (CRC) remain poorly understood." (PMID 34345014, 2021). "First, immunofluorescence staining showed that RNF141 was mainly localized in the cytoplasm and cell membrane in HCT116, SW480, DLD-1, and HT29 cells, which is consistent with the distribution of RNF141 in colorectal cancer tissues." (PMID 34345014, 2021). "Due to RING finger domain, RNF141 is categorized as RING E3 ubiquitin ligase and its roles in cancer, especially colorectal cancer, remain largely unknown." (PMID 34345014, 2021).
uterine corpus endometrial carcinoma (1 paper, 2025). A endometrial carcinoma (disease) that involves the body of uterus. "Gene expression analysis showed limited overall significance, but TAF1 was notably upregulated in uterine corpus endometrial carcinoma (UCEC), while RNF115 and RNF141 were downregulated in the same cancer type." (PMID 40591126, 2025).
cancer (2 papers, 2021 to 2025). A tumor composed of atypical neoplastic, often pleomorphic cells that invade other tissues. "Owing to the target proteins screened out by LC–MS/MS including more than 30 cancer-related proteins, further works are required to elaborate the interaction network of RNF141 that involves in the CRC tumorigenesis." (PMID 34345014, 2021).
tumor (1 paper, 2021). "The subcutaneous xenograft models showed that RNF141 knockdown reduced tumor growth, but its overexpression promoted tumor growth." (PMID 34345014, 2021). "We next established a subcutaneous xenograft model to explore tumor-forming capacity of RNF141 in vivo." (PMID 34345014, 2021). "It appeared that a different location of RNF141 in CRC cells might promote tumor progression through different patterns." (PMID 34345014, 2021). "Nude mice injected with LV-sh-RNF141-infected HCT116 cells were found to have smaller volume and lower weight tumor than those injected with LV-sh-NC-infected cells at the assigned day." (PMID 34345014, 2021). "RNF141 expression did not correlate with gender, age, tumor location, the differentiation degree of tumors, lymph node metastasis, or AJCC stage but correlated with T stage, with a higher expression found in higher T stage (P = 0.019)." (PMID 34345014, 2021).
RNF141 also shares sentences with these, for which no sentence is quoted: breast carcinoma (1 paper).